CCSAP (centriole, cilia and spindle associated protein)
Description:
Plays a role in microtubule (MT) stabilization and this stabilization involves the maintenance of NUMA1 at the spindle poles. Colocalizes with polyglutamylated MTs to promote MT stabilization and regulate bipolar spindle formation in mitosis. Binding of CCSAP to centrosomes and the spindle around centrosomes during mitosis inhibits MT depolymerization, thereby stabilizing the mitotic spindle. May play a role in embryonic development. May be required for proper cilia beating (By similarity).
Synonyms: C1orf96; CSAP; FLJ41471
Tractability: No criterion of Open Targets' tractability assessment is met for any kind of drug.
Gene: Protein-coding gene on chromosome 1 (229,321,011 to 229,343,294, reverse strand). Ensembl gene ENSG00000154429.
Subcellular location: Cytoplasm, cytoskeleton, microtubule organizing center, centrosome, centriole; Cytoplasm, cytoskeleton, spindle; Cytoplasm, cytoskeleton; Cytoplasm, cytoskeleton, cilium basal body; Cytoplasm, cytoskeleton, cilium axoneme; Cell projection, axon; Cell projection, cilium; Cytoplasm, cytoskeleton, microtubule organizing center, centrosome
Gene Ontology:
Molecular function: microtubule binding
Biological process: mitotic spindle microtubule depolymerization; regulation of mitotic spindle assembly; regulation of embryonic development
Cellular component: axon; axoneme; centriole; centrosome; ciliary basal body; ciliary transition zone; cilium; mitotic spindle; mitotic spindle astral microtubule; spindle; cytoskeleton
Genetic constraint (gnomAD): Loss-of-function variants: 16 observed, 16.48 expected, observed/expected ratio (o/e) 0.97, 90% interval 0.66 to 1.47. The synonymous counts are far from expectation, so gnomAD's model fits this gene poorly and the ratio says little. Missense variants: 295 observed, 257.99 expected, observed/expected ratio (o/e) 1.14, 90% interval 1.04 to 1.26. Synonymous variants: 153 observed, 109.51 expected, observed/expected ratio (o/e) 1.4, 90% interval 1.22 to 1.6.
Homologues: Orthologues: chimpanzee CCSAP (99% identical), macaque CCSAP (96% identical), rabbit CCSAP (84% identical), dog CCSAP (83% identical), pig CCSAP (80% identical), guinea pig CCSAP (69% identical), mouse Ccsap (68% identical), zebrafish ccsapb (38% identical), zebrafish ccsapa (29% identical).
Diseases named in the same sentence as CCSAP in open-access papers:
CCSAP is named in the same sentence as 3 diseases in open-access papers, as found by Europe PMC text mining. Sharing a sentence is not in itself a finding about the gene and the disease. The quoted sentences say what the papers report.
tumor (2 papers, 2022). "Four of these intersecting genes, including PTPN1, CHSY1, SIAH1, and CCSAP, were correlated with tumor cell proliferation, migration, and invasion, and we therefore further confirmed their expression levels via RT-qPCR." (PMID 35610725, 2022).
CCSAP also shares sentences with these, for which no sentence is quoted: Chlamydia infection (1 paper); clonorchiasis (1).